INS (insulin)
Diseases named in the same sentence as INS in open-access papers (continued):
Sharing a sentence is not in itself a finding about the gene and the disease.
hepatoma (continued). "Notably, we found that miR-27b levels in human hepatoma cell, Huh7, influence the expression of numerous components of the insulin signaling pathways including the INSR and insulin receptor substrate 1 (IRS1)." (PMID 33212990, 2020). "The fact that we observed a similar perturbation of insulin signaling in different hepatoma cell lines derived from independent clones from different animal species motivated us to investigate the action of insulin on its gluconeogenic targets and on glucose production." (PMID 32694512, 2020). "Finally, to investigate the physiological relevance of these derangements we measured glucose production in primary hepatocytes and in the three hepatoma cell lines exposed to dbcAMP, insulin, or dbcAMP in presence of insulin." (PMID 32694512, 2020). "Finally, the hepatoma cell lines largely dissociated insulin-induced AKT Ser 473 from GSK phosphorylation." (PMID 32694512, 2020). "Surprisingly, besides ESFT cells, β-elemene could inhibit the insulin-driven proliferation and IR phosphorylation in hepatocellular carcinoma and melanoma cells." (PMID 30422809, 2019). "We also tested whether β-elemene could repress the activation of insulin signaling pathway in melanoma cell A2058 and hepatocellular carcinoma cell HepG2." (PMID 30422809, 2019). "We quantified the amounts or the activities of cellular components of rat FAO hepatoma cells stimulated with various doses of insulin and time points—RNA (transcriptomic analysis), key signaling proteins and TFs (western blotting), and metabolites (metabolomic analysis)." (PMID 30267682, 2018). "Insulin has been reported to inhibit SHBG production by hepatoma cells in vitro, suggesting that insulin may be an important regulating factor for SHBG in vivo." (PMID 30100880, 2018). "To determine whether the observed hormonal regulations are not limited to primary rat hepatocytes, we used real-time PCR to examine the effects of insulin and dexamethasone on the Enpp1 mRNA abundance in HepG2 cells, a human hepatoma cell line." (PMID 29513794, 2018). "The human hepatoma cell line HepG2 is frequently used to investigate insulin-dependent pathways, but these cells are derived from a Caucasian male with a differentiated hepatocellular carcinoma and the origin from tumour tissue influences the metabolic phenotype." (PMID 30355754, 2018). "An in vitro experiment showed that incubation of 3T3-L1 adipocytes with insulin results in a significant decrease in the miR-183-5p level; miR-183-5p can inhibit apoptosis in human hepatocellular carcinoma cells and was found upregulated in cirrhotic liver and premalignant lesions." (PMID 25672643, 2015). "Using the human hepatocellular carcinoma cell line HepG2, we also showed that Nck1 depletion by siRNA promotes insulin signaling, as represented by increased levels of pY IRS-1, Akt phosphorylation on Ser473, GSK3β phosphorylation on Ser9 and glycogen synthesis in response to insulin." (PMID 25398386, 2014). "To reveal if hepatic changes by cinnamon supplementation might be ascribed to the liver itself or to brain-insulin action on liver, we analyzed the effect of cinnamon supplementation on insulin signaling in the differentiated rat hepatoma line Fao." (PMID 24643026, 2014). "Hence, hepatocyte cell lines, such as the murine H4IIE and human HepG2 hepatoma-derived cells, can serve to measure the effect of plant preparations on the insulin-dependent and insulin-independent regulations of hepatic glucose metabolism." (PMID 22235232, 2012). "Furthermore, we have expressed human insulin also in various cell lines such as HepG2 (human hepatoma), NIH3T3 (mouse fibroblast) and HeLa (human cervical cancer) cells." (PMID 17941991, 2007). "In addition, mouse α2-HSG (25μg/ml) completely abolishes insulin-inducedDNA synthesis in H-35 rat hepatoma cells." (PMID 11467416, 2001).
hepatoma (continued). "In addition, CTRP7 appears to antagonize insulin signaling since Tyr1131/1146 phosphorylation of the insulin receptor as well as Ser256 phosphorylation of Foxo1 were significantly reduced in insulin/CTRP7 co-treated hepatoma cells." (PMID 36831095, 2023). "However, it is worth of attention that three different hepatoma cell lines from three different species, which have been cultured for years, show remarkable similarities in their aberrant phenotype for insulin signaling, glucose production, and protein electrophoretic profile." (PMID 32694512, 2020). "Overall, a direct comparison of insulin signaling in primary hepatocytes and in hepatoma cell lines is necessary to validate hepatoma cell lines as model to study insulin signaling and insulin action on glucose metabolism, and to better understand the biology of hepatocellular carcinoma (HCC)." (PMID 32694512, 2020). "Moreover, in vitro studies have shown that insulin might inhibit production of SHBG in human hepatoma cells, and in accordance with these findings an inhibitory effect of insulin on SHBG secretion has been reported." (PMID 23781314, 2013). "Insulin stimulates the phosphorylation of PDHA1 at the Ser293 residue, leading to a reduced PDHA1 enzyme activity in HepG2 hepatocellular carcinoma cells." (PMID 37761999, 2023). "The results indicated that tight junction, mTOR, insulin, PI3k-AKT, hepatocellular carcinoma, FoxO, and apoptosis pathways (p < 0.05) were the possible druggable signaling pathways of CVM-1125." (PMID 37351538, 2023). "In hepatoma cells, ROS inhibit IRS1 function in insulin signaling through the induction of IRS1 phosphorylation on Ser307." (PMID 36768755, 2023). "Specifically, insulin enhances the phosphorylation of pyruvate dehydrogenase E1α (PDHA1) at the Ser293 residue and promotes the proliferation of HepG2 hepatocellular carcinoma cells." (PMID 37761999, 2023). "In the previous report, we reported that insulin increased p-ser293 PDHA1 and PKM2 levels in HepG2 and Huh7 hepatocellular carcinoma cells." (PMID 37761999, 2023). "Insulin was reported to increase p-Ser293 PDHA1 (p-PDHA1) levels in HepG2 and Huh7 hepatocellular carcinoma cells." (PMID 35740278, 2022). "In contrast to normal hepatocytes, insulin enhanced p-PDHA1 level and induced proliferation of hepatocellular carcinoma HepG2 cells." (PMID 35740278, 2022). "Pioglitazone, an insulin sensitizer that enhances insulin action and decreases hepatic gluconeogenesis in liver, increased IDE mRNA and protein levels in a time-dependent manner in the mouse hepatoma cell line Hepa 1c1c7." (PMID 33477364, 2021). "Experimental studies using a human hepatoma cell line (HepG2) showed that SHBG expression is negatively affected by monosaccharides (glucose or fructose), insulin and androgens." (PMID 33139661, 2020). "Moreover, insulin may also increase the mRNA level of LDL receptor in hepatoma cells of rats." (PMID 31510106, 2019). "Here, we explored how the hepatoma cell line FAO cells interpret a physiologically dynamic stimulus, induced and basal insulin stimulation." (PMID 30267682, 2018). "To understand how insulin concentrations are interpreted by cells, we constructed a trans-omic network of insulin action in FAO hepatoma cells using transcriptomic data, western blotting analysis of signaling proteins, and metabolomic data." (PMID 30267682, 2018). "At the post-receptor level, prolonged treatment with insulin is known to inhibit JAK2/STATs signaling by reducing JAK2 and STAT5 phosphorylation and protein content of STAT3, e.g., in H4IIE hepatoma cells." (PMID 29977227, 2018). "In vitro, the human hepatoma cell line HuH7 also respond to insulin (10 nM) by up-regulation of GHR, although the study focused on concentrations of insulin superseding physiological levels." (PMID 28486400, 2017). "Namely, low levels of insulin and insulin growth factor (IGF)-1 in CR serum mediate a partial protection against hydrogen peroxide in rat hepatoma cells." (PMID 25711920, 2015).
hepatoma (continued). "Here, we present evidence that ROS promoted the effects of insulin-induced glycolysis and PKM2 expression in the cultured hepatocellular carcinoma cells." (PMID 24895527, 2014). "In five studies using non-malignant cells (human mammary epithelial cells, rat H4-II-E hepatoma cells, and MCF-10A cells, insulin lispro displayed similar mitogenic potency compared to human insulin." (PMID 21714872, 2011). "Our focus on insulin and IGF-1 signaling pathways stemmed from earlier studies demonstrating over-expression of AAH in hepatocellular carcinoma cells and in transgenic mice that over-express IRS-1." (PMID 17156427, 2006). "Our findings are consistent with a study reporting that a short period of ER stress lasting for up to 8h, in which JNKs are activated, did not inhibit insulin-stimulated AKT phosphorylation in Hepatoma cell line HepG2." (PMID 38727305, 2024). "Although one study showed that mTORC1 is required for insulin stimulation of serine phosphorylation of IRS-2 in Fao cells (hepatic carcinoma cells), S6K1 is not required for this effect." (PMID 39163364, 2024). "Indeed, insulin sensitively augmented both PDHA1 and p-PDHA1 levels in hepatocellular carcinoma cell lines." (PMID 35740278, 2022). "Our data indicate that deletion of ChREBP delays insulin-induced hepatocarcinogenesis, suggesting a combined oncogenic and lipogenic function of ChREBP along AKT/mTOR-mediated proliferation of hepatocytes and induction of hepatocellular carcinoma." (PMID 34685767, 2021). "In human hepatocellular carcinoma HepG2 cells grown in normal glucose medium, exposure to insulin for 24-h did not regulate Ide mRNA or protein levels." (PMID 33477364, 2021). "It is therefore not surprising that thousands of studies used hepatoma cell lines, most commonly HepG2 cells, to model hepatocytes in insulin signaling or in metabolism." (PMID 32694512, 2020). "Compared to primary hepatocytes, these hepatoma cell lines also showed defective expression of the key gluconeogenic genes G6P and PEPCK, insulin unresponsive GSK, and dampened glucose production which was unresponsive to either dbcAMP or insulin." (PMID 32694512, 2020). "Notably, we found that miR-27b controls post-transcriptional expression of numerous components of the insulin signaling pathway including the insulin receptor (INSR) and insulin receptor substrate 1 (IRS1) in human hepatoma cells." (PMID 33212990, 2020). "In particular, we observed an enrichment of miR-192-5p target genes involved in telomere maintenance and hepatocellular carcinoma and in the signaling pathway of FOXO1, a transcription factor that plays important roles in the regulation of gluconeogenesis and glycogenolysis by insulin signaling." (PMID 32620541, 2020). "Then, inflammation may impair insulin signaling and exacerbate liver fatty infiltration, even fuel the transition from NAFLD to NASH, and liver cirrhosis, even hepatocellular carcinoma." (PMID 31929982, 2019). "Human hepatoma HepG2 cells that maintain liver cell morphology and function have been cultured with high glucose, with or without high insulin levels, to mimic the different diabetic conditions, such as type 1 and type 2 DM." (PMID 30024975, 2018). "Insulin regulates Egr1 expression in hepatoma cells and in non-liver-derived cells overexpressed with insulin receptors." (PMID 29607419, 2017). "To better characterize the role of miR-155 in regulating insulin sensitivity in liver and SM, we performed in vitro glucose uptake assays [i.e., 18F-FDG (fluoro-D-glucose) uptake assays] using human hepatocellular carcinoma 7402 cells, and murine hepa and C2C12 cell lines." (PMID 27711113, 2016). "We found that insulin increased pyruvate kinase M2 (PKM2) expression through reactive oxygen species (ROS) for regulating glucose consumption and lactate production, key process of glycolysis in hepatocellular carcinoma HepG2 and Bel7402 cells." (PMID 24895527, 2014).
hepatoma (continued). "To discover novel genes that modulate insulin sensitivity and HGP, we developed a high throughput human hepatoma-based G6PC/PDK4 gene expression assay and used it to screen a library containing synthetic small interference RNA (siRNAs) for 6650 genes encoding druggable protein targets." (PMID 22590537, 2012). "Clevudine-induced depletion of mtDNA is not restricted to insulin-secreting cells but is also observed in cultured hepatoma cells or muscle tissue from patients." (PMID 22230186, 2012). "To identify novel drug targets that have the potential to enhance insulin sensitivity and decrease HGP, we generated a human hepatoma cell line, AH-G6PC, that stably expressed β-lactamase under the control of the G6PC promoter as described in the “Experimental Procedures” section." (PMID 22590537, 2012). "It haspreviously been reported that prolonged (8–24 h) but not short-term(4 h) insulin pretreatment inhibits GH signaling via the GHR/JAK2/STAT5Bpathway in rat hepatoma cells." (PMID 21559284, 2011). "Recent studies with hepatoma cells have shown that imatinib inhibits c-Abl cytosolic tyrosine kinase to attenuate insulin-induced but not IGF-1-induced phosphorylation of Akt and GSK-3β." (PMID 19693287, 2009). "Interestingly, it has been shown that in vitro, heparin reduces insulin sensitivity of cultured human lymphocytes, but not adipocytes, erythrocytes or intact hepatoma cells." (PMID 34277977, 2021). "We conclude that hepatoma cell lines do not accurately model the hepatocyte for insulin action but may be valuable tools to investigate the proteomic changes conferring to hepatocellular carcinoma its peculiar metabolisms." (PMID 32694512, 2020). "However, these hepatoma cell lines showed little or no basal AKT Ser 473 phosphorylation which was potently induced by insulin but that was not affected by H-RAS17N." (PMID 32694512, 2020). "The insulin-mimetic ability of Cu2+ and Zn2+ to activate the PI3K/Akt pathway by the interaction with insulin-receptor (IR) and IGF1-receptor (IGF1R) in HepG2 human hepatoma cells, which result in the phosphorylation and nuclear exclusion of transcription factor FoxO1a, has been recently questioned." (PMID 28090201, 2016). "Furthermore, in 3T3-L1 adipocytes and HepG2 hepatoma cells, inhibition of calpain did not affect the insulin-mediated PI3K/Akt pathway but it did prevent the insulin-stimulated glucose uptake." (PMID 22536436, 2012). "However, we could not observe any significant effect of either dbcAMP or insulin on both G6P or PEPCK gene expression in all the tested hepatoma cell lines." (PMID 32694512, 2020). "The ability of amino acids to stimulate signaling even in the absence of insulin, and the synergy of amino acids with insulin, was confirmed for hepatocytes and for other insulin-sensitive cell types, including muscle cells, adipocytes, hepatoma cells, CHO cells and pancreatic β-cells." (PMID 24880909, 2015). "The down-regulation of insulin signaling and PPARα transcription in this analysis reflects the increased expression of gluconeogenesis and lipid synthesis and trafficking genes in the hepatoma cells following Tcf7l2 silencing, as both a negative regulators of these pathways." (PMID 25414334, 2014). "In human hepatoma (HepG2) cells, we observed that protein levels of endogenous LRH-1 are increased by insulin without a change in mRNA levels of LRH-1." (PMID 30923324, 2019). "While healthy hepatocytes do not express the IGF‐1 receptor, due to de‐differentiation, hepatoma cell lines do express the receptor and respond to IGF‐1 by phosphorylating Akt in the same way as insulin." (PMID 29263118, 2017).
renal failure (234 papers, 2001 to 2026). "Hepatic cirrhosis, endocrine conditions and therapy, and pregnancy will elevate insulin requirement, while pancreatic deficiency and renal failure reduce it." (PMID 40035222, 2025). "For example, the false perception that insulin causes kidney failure, as reported in our FGDs, has also been reported previously." (PMID 38694587, 2024). "The occurrence of IR involves multiple signaling pathways; it is also a state in which multiple sites and levels of insulin signaling act together abnormally, which is one of the independent risk factors for kidney injury and renal failure." (PMID 36072812, 2022). "CMR may be preferred in diabetic patients undergoing CABG and patients with renal insufficiency, as they may have difficulties with insulin regimens or are at risk of nephrotoxicity with contrast agents used in PET." (PMID 38953367, 2024). "Atypical insulin activity may lead to renal failure associated with nutritional, metabolic, and circulatory consequences." (PMID 36111327, 2022). "For example, patients with high risk of renal failure or patients treated with insulin ± oral medication were expected to have 20% higher ‘hazard’ of a normal recovery with VRT compared to usual care (HR = 1.20, 95% CI 0.95–1.51 and HR = 1.20, 95% CI 0.99–1.46 respectively)." (PMID 33302878, 2020). "Although speculation, antioxidants may inadvertently increase the risk of renal failure if ROS were equally important for insulin signalling in kidney as in skeletal muscle." (PMID 31195596, 2019). "They expressed doubt over the origin of insulin; concern over insulin side-effects (e.g. hypos); believed that insulin might cause kidney failure and impair pancreatic function." (PMID 24282518, 2013). "Also, he said that insulin is better than tablets, because tablets may have some side effects like kidney failure but insulin if taken in right way and dose it won't cause any side effects’." (PMID 40088007, 2025). "In patients with CKD, age-related muscle loss is deepened by metabolic disorders associated with renal failure such as inadequate nutrient intake, loss of nutrients, catabolic illnesses, acidemia, inflammation, low levels of or resistance to anabolic hormones like insulin, growth hormone, and IGF-1." (PMID 29620449, 2018). "At the tissue and organismal levels, disruption of magnesium homeostasis contributes to metabolic inflexibility, insulin resistance, acute kidney injury, and the progressive decline in stress tolerance that accompanies aging." (PMID 42244260, 2026). "This is particularly true for those with multiple medical conditions, and therefore notably the older individual, as insulin is often indicated where other medical management is more complicated, from cancer to renal failure to heart disease." (PMID 40035222, 2025). "Critical illness indicators such as lactate and acute kidney injury (classified as “complication: other”) were occasionally observed in fluid- and insulin infusion- focused studies." (PMID 40407548, 2025). "Second, the safety of insulin icodec across the different degrees of liver and renal failure is still to be reported with an ongoing trial in patients with hepatic dysfunction." (PMID 38213906, 2024). "For renal systems, elevated incidence risks of acute nephritis and renal failure were both observed when compared with the metformin group, or only increased incidence risks of acute nephritis compared with the insulin injection group." (PMID 39435881, 2024). "Intensive glucose control with Insulin improved in those with multiorgan failure, hospital mortality, bloodstream infection, and acute kidney injury needing dialysis." (PMID 39149651, 2024). "Since most sulfonylureas undergo renal metabolism, DN patients who enter the renal failure stage switch to insulin for hypoglycemic treatment under the doctor’s guidance." (PMID 37833779, 2023).